FYN (FYN proto-oncogene, Src family tyrosine kinase)
Diseases named in the same sentence as FYN in open-access papers (continued):
Sharing a sentence is not in itself a finding about the gene and the disease.
cancer (continued). "Moreover, FYN is involved in the regulation of multiple cancer-related signaling pathways, including interactions with ERK, COX-2, STAT5, MET and AKT." (PMID 36740671, 2023). "Additionally, FYN is highly expressed in many cancers and promotes cancer growth and metastasis through diverse biological functions such as cell growth, apoptosis, and motility migration, as well as the development of drug resistance in many tumors." (PMID 36740671, 2023). "To investigate whether FYN may act as a cancer suppressor gene, we then detected the migration and invasion abilities of FYN-overexpressing Hep3B and Huh-7 cells." (PMID 35397600, 2022). "Furthermore, increased PPP1CC and FYN expression was correlated with increased drug sensitivity to cancer cells, such as PX−316, Ifosfamide, okadaic acid, Chelerythrine, AT-13387, and Amonafide (cor > 0.29 and P < 0.05)." (PMID 33850056, 2021). "Therefore, FYN is considered a pivotal oncogene as a result of its regulatory roles in cancer-related signaling pathways." (PMID 32811808, 2020). "FYN was tyrosine kinases and was an essential molecule in cancer pathogenesis and drug resistance." (PMID 33488678, 2020). "In addition to PTK6, we also observed modest inactivity of FYN, another Src kinase, which plays an important role in cancer as well as diseases of the central nervous system." (PMID 31278310, 2019). "Our published studies have shown that FYN plays an important role in cellular motility in cancer, particularly when driven by hepatocyte growth factor (HGF), which is found in abundance in the plasma of patients with both acinar prostatic adenocarcinomas and NEPC." (PMID 26624980, 2015). "Since COX2 and FYN have been shown to be localized in caveolae like structures in some cancer cells, we speculate that caveolae is one possible site where FYN could be found in the same cellular environment as COX2." (PMID 24970799, 2014). "In addition, several of the promoter-hypermethylated genes were associated with the development of human cancers and these include GIPC2, DIRAS3, TYSPL6, EDNRB, FYN, GDNF, RASSF1, and RASSF2." (PMID 21962230, 2011). "Therefore, we hypothesized that FYN plays a pro-cancer function in GC, and clinical samples from our hospital verified this conclusion." (PMID 37016377, 2023). "Consequently, we speculated that miR-146a-5p might suppress the malignant transformation of cancers by controlling protein-tyrosine kinases activity, targeting FYN." (PMID 31285693, 2019). "We discovered and validated that concurrent targeting of FYN, along with other tyrosine kinases such as IGF1R, EGFR, or ABL2 can synergistically eradicate TNBC and impede cancer growth." (PMID 40243589, 2025). "For example, in the DLX4 gene module, connections among DLX4, the known cancer gene ABL1, and four candidate AML genes (SP1, FYN, GRB2, and SMAD2) co-occurred in multiple patients." (PMID 39013885, 2024). "Therefore, we speculate that FYN may play a pro-cancer role in GC." (PMID 37016377, 2023). "Thus, FYN may play a dual role in the development of cancer." (PMID 37016377, 2023). "Among the common kinases, the mTOR, AKT1, SRC, FYN, and GNB2L1 are the kinases that are common in ALS and cancers and also identified as hub genes from the PPI network." (PMID 36590916, 2022). "All six HUB nodes correlated with at least one cancer type, and FYN and PSMB2 correlated with poor OS in patients with five different cancers." (PMID 32933107, 2020). "In particular, SRC together with YES, FYN and LYN were often found co-overexpressed in our cancer cell lines and tissue sections." (PMID 29937990, 2018). "While the overexpression/hyperactivation of SRC is associated with poor prognosis in patients suffering from various cancers, similar studies for LYN and FYN led to varied conclusions." (PMID 29937990, 2018).
cancer (continued). "Another complicating aspect of studying c-SRC’s role in cancer biology is the high degree of structural relatedness with other SRC family tyrosine kinases (SFKs), first and foremost the ubiquitously expressed FYN and YES." (PMID 27562229, 2016). "Analyzing gene expression data from 42 ccRCCs in the International Cancer Genome Consortium revealed that SLC1A1, GRIA3 and FYN mRNA abundance was each significantly correlated with the expression of six known HIF target genes." (PMID 25326682, 2014). "Of the genes differentially expressed between two group cancers, HTR2B, CHL1, the ZNF family, YWHAZ and FYN were the most significantly altered." (PMID 24597767, 2014). "Some up-regulated genes such as ACVR1B, FYN and CTTN, and some down-regulated genes such as PTEN, are known to be correlated with cell migration and cancer metastasis." (PMID 21998723, 2011). "FYN is an essential regulator of the AKT signaling pathway, which commonly participates in abnormal cell proliferation and therapeutic resistance in many cancers." (PMID 40296913, 2025). "MAG1, FYN, and TBRG1 have been investigated in the context of cancer and cellular migration, which may provide insights into immune cell dynamics and the regulation of inflammatory pathways." (PMID 40141401, 2025). "Ablation of KDM5, which has been shown to induce drug tolerance in cancer cells, did not significantly alter FYN expression." (PMID 40243589, 2025). "Through the analysis of FYN in KIRC and KIRP, we found that the dysregulation of FYN by DNA methylation could significantly affect the prognosis of cancer patients." (PMID 36945884, 2023). "In our study, we confirmed the pro-cancer role of FYN/TOPK axis in GC progression, and inhibition of FYN or TOPK could significantly delay the progression of GC." (PMID 37016377, 2023). "FYN overexpression significantly inhibited A549 cell viability, invasion, migration, and angiogenesis, accelerated cell apoptosis, and inhibited E-cadherin, vimentin, Snail, and PI3K/AKT protein expression in cancer cells." (PMID 36276113, 2022). "Another very prominent pathway in cancer is ERK/MAPK signaling (p = 3.47 × 10−2; ESR1, FYN, ITGA3, PIK3R3, PLA2G4A, PLA2G5, RPS6KA5), which is the core of the signaling network involved in regulating cell growth, development, and division and a target of many cancer therapeutics." (PMID 35106465, 2022). "FYN is a nonreceptor tyrosine kinase in the Src family of kinases that plays critical roles in the development and progression of many cancers by regulating morphogenic transformation, cellular motility, cell growth, and cell death." (PMID 32811808, 2020). "FYN signaling pathways regulate cell adhesion, drive epithelial-to-mesenchymal transition (EMT), and play a role in migration, cancer cell growth and motility, cancer progression, as well as antiapoptotic activity." (PMID 33233470, 2020). "Among them are genes involved in cell adhesion/migration processes (PEPD), migratory potential of cancer cells (ACTN1), ECM (LTBP2, PRG4, ADGRL1, CD9), or in metabolic processes (LDHD, ALDH7A1), as well as proto-oncogenes or their ligands/inhibitors (FYN, PPP1R13L)." (PMID 30838002, 2019). "In addition to regulating cell death, FYN and LYN participate to cancer cell invasion and metastasis." (PMID 29937990, 2018). "In patient P4, two of four malignant ascites-emerging clones may be targetable by inhibitors against BRAF (e.g. Vemurafenib), TEP1, ERBB4, PIK3CA, HDAC9, or FYN." (PMID 26811494, 2016). "FYN (0.95% of cases) and PRKCA (1.58% of cases) have not been listed as driving genes by CGC, but studies have found that they are associated with many cancers and overexpressed in cancer patients." (PMID 34560840, 2021). "We found that FYN and PPP1CB were negatively correlated with RNAss, while PPP1CC was positively correlated with RNAss, which indicated that prognostic genes might have a relationship with cancer cell sensitivity or resistance to chemotherapy treatment." (PMID 33850056, 2021).
cancer (continued). "To investigate this further, we assessed whether simultaneous inhibition of FYN by PP2, which selectively targets the SRC family kinase inhibitor with the highest potency against FYN, in combination with other kinase inhibitors (TKIs), could inhibit cancer cell growth." (PMID 40243589, 2025). "However, the current research on the biological role of FYN in tumor inhibition is mainly pro-cancer, but we do not know whether FYN also plays a anti-cancer role in other unstudied tumors." (PMID 36740671, 2023). "Having demonstrated that activation of AMPA-type glutamate receptors stimulates FYN → ERK signaling that results in the proliferation of hypoxic Hep3B cells, we next asked whether inhibiting this pathway using the AMPA receptor antagonist GYKI 52466 would have anti-cancer effects in vivo." (PMID 25326682, 2014). "FYN is a nonreceptor tyrosine kinase, specifically a Src family kinase (SFK), that plays a critical role in the development and progression of several cancer types by regulating morphogenic transformation, cellular motility, cell growth, and cell death." (PMID 32811808, 2020). "FYN is a non-receptor tyrosine kinase belonging to the SRC family of kinases, which are frequently over-expressed in human cancers, and play key roles in cancer biology." (PMID 26848862, 2016).
tumor (60 papers, 2007 to 2026). "The role of FYN in tumorigenesis has been extensively studied and has been demonstrated to promote tumor cell growth and migration." (PMID 40958910, 2025). "Meanwhile, the increased FYN expression was associated with the upregulation of p‐Akt and total Akt in KMT2B‐overexpressing tumour tissues." (PMID 40741875, 2025). "A variety of preclinical studies have also demonstrated that FYN/SRC inhibitors inhibit multiple tumor progressions." (PMID 36740671, 2023). "In vivo experiments also confirmed that silencing FYN inhibited tumor growth, and H&E results showed that cells in the control group proliferated more actively than those in the shFYN group." (PMID 37016377, 2023). "FYN is therefore an attractive therapeutic target for various tumor types, and suppressing FYN can improve the prognosis and prolong the life of patients." (PMID 36740671, 2023). "Microarray transcriptomic and bioinformatic analysis of ovarian cancer identified FYN as a key downstream target in the transcriptome of GNAi2/gip2 regulated tumor progression." (PMID 36740671, 2023). "Tissue microarrays containing HCC tissue samples (n = 61) and non-tumor tissue (n = 19) samples were examined for FYN expression by IHC." (PMID 35397600, 2022). "As expected, the FYN overexpression group had significantly reduced the tumor volume and weight compared with the control group." (PMID 35397600, 2022). "Seven tumor antigens (ADA, FYN, HDC, NFKBIZ, RASSF4, SLC6A3, and UPP1) associated with inferior prognoses and higher-level infiltration of antigen-presenting cells in PRAD were identified, thus promising candidates for mRNA vaccine." (PMID 35547260, 2022). "On the contrary, the high level of FYN was negatively correlated with the C1 (P < 0.05), suggesting its tumor-suppressive role in HCC." (PMID 33850056, 2021). "In phospho-proteomic studies, activator phosphorylation sites on FYN demonstrate a two-fold increase in tumor tissue compared to wild type pancreatic patient tissue." (PMID 33233470, 2020). "FYN was also found overexpressed in NSCLC tumours as compared to normal tissue, but the prognostic impact of this was not investigated." (PMID 29937990, 2018). "The observation that LYN and FYN are widely overexpressed NSCLC tumours while being undetectable in normal lung tissue is consistent with the previously suspected involvement of these SFKs in transformation and tumourigenesis." (PMID 29937990, 2018). "In the group of genes that shows high expression in tumours with favourable outcome, genes related to cell differentiation (FYN, NTRK1) and neuronal development (DCAMKL1) can be found." (PMID 17531100, 2007). "The pro‐tumour effects of the KMT2B/FYN axis are mediated by the PI3K/Akt signalling pathway." (PMID 40741875, 2025). "Additionally, FYN mRNA level was upregulated in GC tumor samples compared with it in normal tissues from TCGA." (PMID 37016377, 2023). "However, the relationship between FYN and apoptosis is controversial, and some studies have demonstrated that FYN promotes apoptosis in tumor cells." (PMID 36740671, 2023). "Consistently, immunohistochemical staining and TUNEL assays assay of tumor tissues also confirmed that the FYN overexpression group exhibited a remarkable decrease of Ki67 positive cells along with an increasing number of apoptotic cells compared with the control group." (PMID 35397600, 2022). "The xenograft model showed that overexpression of FYN could significantly inhibit malignant tumor behaviors and promote tumor cell apoptosis." (PMID 35397600, 2022). "Elevated expression level of FYN (p value = 0.000), LCP2 (p value = 0.002), PTPRC (p value = 0.011), WAS (p value = 0.005), ZAP70 (p values = 0.000) and NCF4 (p values = 0.047) were associated with tumor size." (PMID 34834481, 2021). "High expression of FYN and high FYN kinase activity are restricted to low-stage tumours." (PMID 17531100, 2007).
tumor (continued). "In the TCGA LIHC and GTEx datasets, SRC and YES1 were also significantly upregulated in tumor tissues relative to normal liver tissues (p < 0.01 for both), while FGR and FYN remained unchanged." (PMID 40650282, 2025). "Fyn tyrosine kinase (FYN), a key Src family kinase (SFK), drives tumor development and progression by regulating cell adhesion, invasion, proliferation, survival, apoptosis, and angiogenesis." (PMID 40003950, 2025). "VEGFC, FGF1, INHBA, FYN, and AGTR1 promote angiogenesis, lymphangiogenesis, EMT, invasion, and tumor cell survival – constituting pro-metastatic signaling." (PMID 41006647, 2025). "Our approach provided a significant number of genes related to T cell function in the tumor microenvironment, including HSP90AA1, ETS1, CXCR4, RGS1, and FYN, all detected at the gene level." (PMID 39548591, 2024). "CCL14, FYN, NOD1, and GDF10 mRNA expressions were decreased in tumor tissues compared with the adjacent non-tumor tissues." (PMID 38602568, 2024). "This interaction triggers a signaling cascade within the tumor cells, activating the intracellular PDE3B pathway via FYN-mediated integrin signaling." (PMID 39727934, 2024). "FYN drives G6PD by phosphorylating STAT3 expression, leading to the promotion of tumor growth and inhibition of cellular senescence." (PMID 36740671, 2023). "Subsequently, we applied the COX regression model and conducted ROC analysis to identify the final set of tumor-related genes (TRGs), which included CASP4, FYN, TOB1, and CLEC2B." (PMID 37753069, 2023). "Among these genes, FCGR2A, FYN, ITGB2, and VSIG4 protein levels were increased in tumor tissues, while MMP9 protein level was decreased, which was consistent with their mRNA expression levels." (PMID 38022584, 2023). "We found that BMX and FYN had lower expression levels in HCC tumour tissues, whereas KPNA2, PFKFB4, and SPP1 had higher expression levels in HCC tumour tissues." (PMID 36873244, 2023). "Lastly, in CR-TNBC patient P942, the baseline PDX tumor (BTY14) had high phosphorylation on the shared pTyr sites of SRC, FYN, LCK, YES1, and FGR as well as SFK substrates such as tensin, SHIP-1 (INPP5D), AFAP1L2, paxillin, and PTK2." (PMID 36077757, 2022). "Eight hub genes (CDK1, EGFR, UBC, MYC, CCNB1, RHOB, CDC6, and CDC20) have tumor suppressor functions, while five hub genes (CDK1, EGFR, FYN, UBC, and CCNB1) are protein kinases as well." (PMID 35632527, 2022). "The intratumoral heterogeneity was also explored using the Tumor Purity value, with which CXCL11, ERAP2, FYN, GH1, MAP3K14, and SEMA6C were found negatively correlated, while the rest were positively correlated." (PMID 36428747, 2022). "In this study, using RNA-seq data of 576 HCC patients, a panel of seven genes (including LCP2, TYROBP, ZAP70, PTPRC, FYN, WAS and NCF4) has been identified which are independent predictors of delayed tumor recurrence and improved patient prognosis." (PMID 34834481, 2021). "We found that numerous NK cell effector function-related genes, such as TBX21, FYN, NCR1, SH2D1A, SH2D1B, PTPN6, and IL18RAP, were downregulated in tumor-infiltrating NK cells." (PMID 34535671, 2021). "In particular, downregulation of LYN and/or FYN, that we find overexpressed in primary NSCLC tumours as compared to normal lung, impairs the growth of NSCLC cells." (PMID 29937990, 2018). "FAK signaling has been shown to regulate proteins (e.g. SRC, SYK, FYN, LYN, GRB2, PI3K, and paxillin) that are involved in modulating cytoskeleton rearrangements to enhance tumor growth and metastasis." (PMID 27472394, 2016). "In summary, our studies demonstrate that FYN plays an important role in NEPC metastasis and progression in a xenograft tumor model." (PMID 26624980, 2015). "Notably, RGS1, CBLB, and FYN were expressed at higher levels, while IFNG was expressed at lower levels across all tumor-infiltrating NK clusters compared to the preinfusion NK clusters." (PMID 40315330, 2025).